LEP (leptin)
Diseases named in the same sentence as LEP in open-access papers (continued):
Sharing a sentence is not in itself a finding about the gene and the disease.
osteophytes (2 papers, 2010 to 2025). "This may explain why previous reports suggested that both leptin and IL-6 are highly expressed in osteophytes, yet we were unable to describe any associations between osteophytes and serum levels of either." (PMID 20482813, 2010). "COMP had an AUROC of 0.604 (0.543,0.664) for new cases of JSN, COMP, IL-1β and leptin had an AUROC 0.586 (0.524,0.646) for new osteophytes, and TNF-α, IL-1β and adiponectin had an AUROC 0.590 (0.520,0.659) for new sclerosis." (PMID 41194279, 2025). "We found that serum leptin levels in both sexes and serum IL-6 levels in women were positively associated with hip JSN, but not with osteophytes." (PMID 20482813, 2010). "We found no significant relations between leptin, IL-6, and the presence or severity of osteophytes (data not shown)." (PMID 20482813, 2010).
Pain (2 papers, 2022). An unpleasant sensory and emotional experience associated with actual or potential tissue damage, or described in terms of such damage. "In addition, the role of leptin and its influence on the HPA-axis and its role with painful disorders have been investigated." (PMID 35063029, 2022).
pancreatic neuroendocrine neoplasm (2 papers, 2023). A neoplasm with neuroendocrine differentiation that arises from the pancreas. "Leptin and adiponectin are adipokines involved in the carcinogenesis of gastrointestinal cancers, even though no clear link with pancreatic neuroendocrine neoplasms (PanNENs) has yet been investigated." (PMID 37444627, 2023).
peripheral artery disease (2 papers, 2021). "In addition, a high leptin level has been associated with peripheral artery disease." (PMID 34207835, 2021).
postmenopausal osteoporosis (2 papers, 2020 to 2024). Metabolic disorder associated with fractures of the femoral neck, vertebrae, and distal forearm. "This study aims to review further the effect of Zhuang-Gu-Fang on the ultrastructure of osteoblasts, bone metabolism balance, and serum Leptin, Ghrelin, and PYY concentration in ovariectomized rats and explore the treatment of postmenopausal osteoporosis with Zhuang-Gu-Fang-related mechanisms." (PMID 33281915, 2020). "Conclusively, the study proved the therapeutic potential of the Zhuang-Gu-Fang for postmenopausal osteoporosis (PMOP) and further revealed that its therapeutic effect was related to the balance of bone metabolism and the recovery effects of bone-related factors Leptin, Ghrelin, and PYY." (PMID 33281915, 2020).
premalignant oral lesions (2 papers, 2015 to 2023). "Compared to healthy controls, patients with premalignant oral lesions had increases in their systemic levels of the inflammatory cytokines IL-6 and IL-17, and increases in the adipokine, leptin." (PMID 26120967, 2015). "The leptin to adiponectin ratio is 1.12 × 10−3 for control subjects, 4.27 × 10−3 for subjects with premalignant oral lesions, 0.65 × 10−3 for subjects with HNSCC and 3.01 × 10−3 for HNSCC subjects that received 1,25(OH)2D3 treatment." (PMID 26120967, 2015). "IL-17 and leptin in each patient with premalignant oral lesions showed a significant correlation between the increased levels of leptin and the increased levels of IL-17 (r = 0.8049, p < 0.0001)." (PMID 26120967, 2015). "The present study also showed increased serum levels of pro-inflammatory cytokines IL-6 and IL-17, and in levels of leptin in patients with premalignant oral lesions or in HNSCC patients treated with 1,25(OH)2D3, which is inverse to what is seen for adiponectin." (PMID 26120967, 2015). "This association was not, however, as prominent as for levels of IL-17 and leptin in patients with premalignant oral lesions." (PMID 26120967, 2015).
primary biliary cirrhosis (2 papers, 2018 to 2022). "However, the food and drug administration (FDA) approval of TUDCA for the treatment of primary biliary cirrhosis and its inhibitory potential against influenza A viral replication by inducing ER stress are to be controversial for its application in leptin/leptin signaling impaired pathologies." (PMID 29868503, 2018).
protein deficiency (2 papers, 2010 to 2016). "While it is well known that maternal undernutrition or protein deficiency leads to underweight pups at birth and a shift in the leptin surge, we previously showed severely suppressed levels of plasma leptin in pups and adults exposed to undernutrition during the postnatal period." (PMID 27146259, 2016). "While it is known that maternal under-nutrition or protein deficiency leads to underweight pups at birth and a shift in the leptin surge, the consequences of under- and over-nutrition on circulating leptin during the post-natal period have not been previously been described." (PMID 20574519, 2010).
retinal degeneration (2 papers, 2017 to 2022). Degeneration of the retina. "Müller cells produce protective factors including IL-6 and leptin in response to stress-induced retinal degeneration and regulate photoreceptor protection." (PMID 28767729, 2017).
retinal disease (2 papers, 2018 to 2019). "Third, a selection bias is possible since data were derived from a case–control study designed to examine the association of novel biomarkers including leptin with renal and retinal diseases." (PMID 30893833, 2019).
scleroderma (2 papers, 2023 to 2025). Scleroderma is a rare autoimmune connective tissue disorder characterized by abnormal hardening of the skin and, sometimes, other organs. "Of note, the serum leptin level of scleroderma patients showed a significant positive correlation with the maximal P wave interval, which can be related to the proinflammatory effect of the leptin." (PMID 39857802, 2025). "We are the first to report low levels of leptin in patients with SSc sine scleroderma compared to subjects with cutaneous involvement (both lcSSc and dcSSc)." (PMID 37753072, 2023).
serous ovarian cancer (2 papers, 2015 to 2018). "To externally validate the adverse effects of high leptin levels on survival, we downloaded the serous ovarian cancer TCGA database and analyzed it using the bioinformatics tools provided at cBioPortal website." (PMID 26053184, 2015). "Therefore, we measured serum and ascites leptin levels by ELISA in samples obtained from healthy BMI and overweight high-grade serous ovarian cancer patients." (PMID 26053184, 2015).
status epilepticus (2 papers, 2018 to 2023). Status epilepticus is defined as a continuous seizure lasting more than 30 min, or two or more seizures without full recovery of consciousness between any of them. "Similarly, the neuroprotective effect of leptin in the status epilepticus induced by kainic acid or pilocarpine was also reported." (PMID 30319532, 2018). "Some of the TBI studies that report weight data also suggest mechanisms for the observed weight deficits including poor appetite, changes in leptin levels, acute stress, and nonconvulsive status epilepticus." (PMID 37471309, 2023).
substance abuse (2 papers, 2013 to 2019). The use of a drug for a reason other than which it was intended or in a manner or in quantities other than directed. "Depending on the anatomical target, central leptin signaling was considered to participate into regulating many DA-dependent behaviors, such as substance abuse, locomotor activity, enforced leaning, food intake, sleep and adaptive behaviors." (PMID 24223863, 2013).
thymus (2 papers, 2017 to 2024). "Administration of leptin had stimulatory effect on the thymus, while leptin-deficient ob/ob mice were characterized by severe thymus atrophy." (PMID 39061983, 2024). "Both cause elevated levels of cortisol, which animal studies have found to cause thymus atrophy, similar to low levels of leptin." (PMID 28288591, 2017).
trypanosomiasis (2 papers, 2018 to 2021). Infection with protozoa of the genus trypanosoma. "Since parasite infects many organs including adipose tissue which is a source to a variety of adipokines, including leptin and could have significant role in pathogenesis of Trypanosomiasis." (PMID 30534129, 2018).
urinary tract infection (2 papers, 2023 to 2024). "A potential role for urinary leptin as a biomarker for treatment efficacy may also exist in urinary tract infections of children, as leptin levels in the urine of children with urinary tract infections declined during therapy." (PMID 37189804, 2023).
venous thromboembolism (2 papers, 2018 to 2025). Occlusion of the lumen of a vein by a thrombus that has migrated from a distal site via the blood stream. "It suggests that a high leptin level may increase the risk of venous thromboembolism (VTE) in animal studies." (PMID 29794796, 2018).
ventricular tachycardia (2 papers, 2018 to 2019). A disorder characterized by an electrocardiographic finding of three or more consecutive complexes of ventricular origin with a rate greater than a certain threshold (100 or 120 beats per minute are commonly used). "Further, they found that high-dose leptin reduces heart rate and sometimes causes sinus pauses and ventricular tachycardia." (PMID 31019683, 2019).
viral pneumonia (2 papers, 2014 to 2021). Inflammation of the lung parenchyma that is caused by a viral infection. "We reasoned that the resistance of the db/db mice to sterile lung injury and fibrosis and their sensitization to viral pneumonia might be attributable to loss of the Type I cytokine function of leptin in the lung." (PMID 25232724, 2014).
vitiligo (2 papers, 2023 to 2024). Generalized well circumscribed patches of leukoderma that are generally distributed over symmetric body locations and is due to autoimmune destruction of melanocytes. "In mice, LEPTIN deficiency ameliorated the development of vitiligo and reduced the expression of Cxcl9, Gzmb, Ifng, and Mx1 in vitiligo lesions." (PMID 38421796, 2024). "Leptin deficiency also resulted in significantly lower expressed vitiligo-related genes, such as Cxcl9 (p = 0.0497), Gzmb (p < 0.001), Ifng (p = 0.0159), and Mx1 (p < 0.001) after modeling." (PMID 37207234, 2023). "Lep KO mice with Leptin deficiency had smaller depigmentation areas and longer depigmentation time than C57 BL/6 WT mice, suggesting that Leptin plays an important role in the occurrence and development of vitiligo." (PMID 37207234, 2023). "However, there are few studies on the association between leptin and vitiligo." (PMID 37207234, 2023). "It is worth noting that the mRNA expression level of LEPR was significantly up-regulated in vitiligo skin lesions (P = 0.013), while LEP wasn’t." (PMID 37207234, 2023). "We also found that serum leptin was decreased while the expression of LEPR was increased in patients with vitiligo." (PMID 37207234, 2023). "Due to the limited sample size of this study, the specific mechanism of leptin’s effect on vitiligo by affecting CD8+ T cells and other pathways needs to be further studied with a larger sample size." (PMID 37207234, 2023). "The serum leptin level of vitiligo patients was significantly lower than that of healthy controls (p = 0.0245)." (PMID 37207234, 2023). "Our research confirmed that abnormal leptin levels can lead to secretion of more cytotoxic factors by CD8+ T cells, and leptin deficiency can alleviate the disease symptoms of vitiligo." (PMID 37207234, 2023). "The result showed that the serum leptin concentration of vitiligo patients was significantly lower than that of healthy controls." (PMID 37207234, 2023). "The effect of Leptin on the occurrence and development of vitiligo remains obscure." (PMID 37207234, 2023). "Leptin could promote the progression of vitiligo by enhancing the cytotoxic function of CD8+ T cells." (PMID 37207234, 2023). "However, serum leptin in vitiligo patients was significantly lower than in healthy controls (p = 0.0245)." (PMID 37207234, 2023). "This study further explored the specific mechanism by which LEP affects CD8+ T cells in vitiligo." (PMID 37207234, 2023). "We proposed a hypothesis that Leptin positively regulates the expression of LEPR in vitiligo, and patients with vitiligo have higher uptake and utilization of leptin than healthy controls." (PMID 37207234, 2023). "A vitiligo model was established by monobenzone on Leptin KO mice." (PMID 37207234, 2023). "Leptin may further promote the occurrence and development of vitiligo disease by affecting cell adhesion molecules." (PMID 37207234, 2023). "Leptin, as a bridge between lipid metabolism and immune regulation, may play an important role in the development of vitiligo." (PMID 37207234, 2023). "LEP or LEPR may become a new target for the treatment of vitiligo." (PMID 37207234, 2023). "Enrichment analysis verified that lipid metabolism is likely to be closely related to the pathogenesis and disease progression of vitiligo, especially the PPAR signaling pathway, of which LEP and LEPR are representative genes." (PMID 37207234, 2023). "Notably, abnormal leptin levels do not necessarily cause vitiligo." (PMID 37207234, 2023). "This study confirmed the effect of leptin on the occurrence and development of vitiligo by enhancing the cytotoxic function of CD8+T cells, revealing an inseparable relationship between lipid metabolism pathways and vitiligo." (PMID 37207234, 2023).
vitiligo (continued). "In conclusion, leptin plays an important role in the pathogenesis and development of vitiligo, but does not constitute sufficient and necessary conditions for the onset of vitiligo." (PMID 37207234, 2023). "Leptin can enhance the cytotoxic function of CD8+ T cells and may promote the occurrence and development of vitiligo diseases by affecting cell adhesion molecules." (PMID 37207234, 2023).
21-hydroxylase deficiency (1 paper, 2024). "Fasting blood was obtained for visfatin, leptin, adiponectin, glucose, insulin, CRP, lipid panel, total cholesterol (TC), triglycerides (TG) and HbA1c, as well as standard laboratory tests to assess adrenal control, from children with CAH due to 21-hydroxylase deficiency." (PMID 39175574, 2024).
abdominal aortic aneurysm (1 paper, 2020). Enlargement and ballooning of the vessel that supplies arterial blood to the abdomen, pelvis and legs. "GRK2 expression positively correlates with myeloid- (CD68) and lymphoid-specific (CD3, CD4, and CD8) markers and with leptin in PVAT from patients with abdominal aortic aneurysms." (PMID 33020373, 2020).
absence seizures (1 paper, 2021). "Likewise, i.p. administration of 25 mg/kg PTZ into leptin-deficient mice and their wild-type counterparts induced absence seizures, myoclonic seizures, generalized clonic and clonic–tonic seizures but the proportion of absence seizures were higher." (PMID 34122016, 2021).
adenovirus infection (1 paper, 2013). "Previous studies using mouse models with altered AMPKα2 activity due to adenovirus infection or AMPKα2-deficiency implicated hypothalamic AMPKα2 in leptin-induced reduction in feeding and body weight." (PMID 23418591, 2013).
adrenal cancer (1 paper, 2024). A carcinoma involving a adrenal gland. "This relationship between adropin and leptin is intriguing, as both proteins act antagonistically during energy homeostasis and the proliferation of adrenal cancer cells." (PMID 39201370, 2024).
Adrenal insufficiency (1 paper, 2023). Insufficient production of steroid hormones (primarily cortisol) by the adrenal glands. "Previous studies have shown acquired adrenal insufficiency, with inverse correlations between serum corticosterone and serum leptin in OLETF rats as compared to LETO." (PMID 37298724, 2023).
adrenal tumors (1 paper, 2024). "It is possible that leptin acting through LepR1 via the MAPK-dependent signaling pathway inhibits cell proliferation in adrenal tumors." (PMID 39201370, 2024). "In our investigation, we identified the mRNA expression of various LepR isoforms across all analyzed types of adrenal tumors, providing evidence that supports leptin’s potential involvement in adrenal tumorigenesis." (PMID 39201370, 2024).
adrenocortical carcinoma (1 paper, 2024). "The effects of human leptin treatment on cell proliferation were assessed using the NCI-H295R adrenocortical cancer cell line model." (PMID 39201370, 2024). "Based on our research, we can assume that leptin inhibits the proliferation of adrenocortical carcinoma cells." (PMID 39201370, 2024).
Age-related cataract (1 paper, 2023). A type of cataract (opacification of the lens) that forms during the course of aging. "Reports have already been published, suggesting the involvement of leptin in the mechanisms underlying the development of age-related cataracts." (PMID 37892980, 2023).
agranulocytosis (1 paper, 2023). "Several genetic variants, such as LEP and HLA polymorphisms, were reported to be associated with clozapine side effects, such as weight gain and agranulocytosis in the current review." (PMID 36980961, 2023). "In addition, clozapine-related weight gain was associated with LEP, SNAP-25 genes, and agranulocytosis risk with HLA-related polymorphisms." (PMID 36980961, 2023).
allergic contact dermatitis (1 paper, 2014). An inflammatory skin condition caused by an immune response to direct contact between the skin and an allergen. "Therefore, inclusion of adiponectin and leptin in severity assessment of allergic contact dermatitis may not be clinically useful." (PMID 25183967, 2014).
ANCA associated vasculitis (1 paper, 2015). "Leptin also seems to decrease in patients with active ANCA associated vasculitis." (PMID 26425347, 2015).
aortic valve disease (1 paper, 2024). "The results of our research indicate a modest association between fibro-calcific aortic valve disease and a decrease in adiponectin or an increase in leptin levels." (PMID 39335491, 2024). "Leptin represents a potential pharmacological target for cardiovascular disorders, including aortic valve disease." (PMID 39335491, 2024).
Apathy (1 paper, 2022). Apathy is a quantitative reduction of interest, motivation and the initiation and persistence of goal-directed behavior, where often the accompanying emotions, thoughts, and social interactions are also diminished. "Among AD patients, compared with those without apathy, those with apathy had higher levels of interleukin-6, interleukin-10, and leptin." (PMID 36572691, 2022).
apical periodontitis (1 paper, 2022). "Additionally, it has been shown that rats with high-fructose diets display increased intestinal leptin levels 28 days after apical periodontitis induction." (PMID 35216099, 2022).
aristolochic acid nephropathy (1 paper, 2011). "Our findings demonstrate the first that AA could induce secretion and expression of fibrogenic leptin in kidney fibroblasts, which reveal potential involvement of leptin in the progression of kidney fibrosis in aristolochic acid nephropathy." (PMID 21304902, 2011). "Taken together, our findings demonstrate that leptin synthesis and secretion were upregulated by AA through PI3K-Akt and C/EBP α activated pathway in renal fibroblasts, which might contribute to the progression of kidney fibrosis in aristolochic acid nephropathy." (PMID 21304902, 2011).
Arterial thrombosis (1 paper, 2017). The formation of a blood clot inside an artery. "A causal relation between leptin and CVD is not clear, although high leptin levels have been shown to be correlated with enhancing platelet aggregation and arterial thrombosis and promoting angiogenesis." (PMID 28278178, 2017).
Arthralgia (1 paper, 2022). "Leptin is a pro-inflammatory adipokine that is highly elevated in obese individuals in which leads to deforming cartilage and be involved in the pathogenesis of arthralgia." (PMID 35941605, 2022).
asthenospermia (1 paper, 2018). "The first study was performed on 79 men with asthenospermia ([leptin] = 4.72 ng/mL) and 77 control men ([leptin] = 3.75 ng/mL)." (PMID 29971101, 2018).